PRAMEF25 (PRAME family member 25)
Tractability: No criterion of Open Targets' tractability assessment is met for any kind of drug.
Gene: Protein-coding gene on chromosome 1 (13,068,677 to 13,077,884, forward strand). Ensembl gene ENSG00000229571.
Gene Ontology:
Molecular function: ubiquitin-like ligase-substrate adaptor activity
Biological process: proteasome-mediated ubiquitin-dependent protein catabolic process; negative regulation of apoptotic process; negative regulation of cell differentiation; negative regulation of DNA-templated transcription; positive regulation of cell population proliferation
Cellular component: Cul2-RING ubiquitin ligase complex; cytoplasm
Homologues: Orthologues: mouse Pramel13 (45% identical), rat Pramef12 (44% identical), rat Pramef8 (43% identical), mouse Pramel12 (43% identical), mouse Pramel15 (43% identical), rat LOC120103107 (42% identical), rat Pramef20 (42% identical), mouse Pramel16 (42% identical), mouse Pramel31 (42% identical), rat Pramef5 (42% identical), rat Pramef20l1 (42% identical), rat Pramel36l1 (42% identical), and 78 more. Paralogues in human: PRAMEF26 (100% identical), PRAMEF15 (97% identical), PRAMEF5 (96% identical), PRAMEF6 (96% identical), PRAMEF4 (96% identical), PRAMEF9 (96% identical), PRAMEF11 (96% identical), PRAMEF27 (96% identical), PRAMEF20 (82% identical), PRAMEF12 (62% identical), PRAMEF8 (61% identical), PRAMEF7 (61% identical), and 12 more.